AREG (amphiregulin)
Diseases named in the same sentence as AREG in open-access papers (continued):
Sharing a sentence is not in itself a finding about the gene and the disease.
triple-negative breast carcinoma (2 papers, 2024 to 2025). An invasive breast carcinoma which is negative for expression of estrogen receptor (ER), progesterone receptor (PR), and human epidermal growth factor receptor 2 (HER2). "We also find that ATP-mediated senescence of lung fibroblasts promotes the growth and enhances the tumorigenic potential of triple-negative breast cancer (TNBC) cells through the release of amphiregulin." (PMID 38460941, 2024). "Finally, the authors demonstrated that ATP-stimulated lung fibroblasts secreted amphiregulin, which enhanced the growth of triple-negative breast cancer cells." (PMID 38977636, 2025). "Finally, we show that conditioned medium derived from senescent lung fibroblasts, which were induced to senesce through the activation of ATP/P2Y11R-mediated signaling, promoted the proliferation of triple-negative breast cancer cells and their tumorigenic potential by secreting amphiregulin." (PMID 38460941, 2024).
acute graft versus host disease (1 paper, 2021). A syndrome of immunologically mediated tissue damage that may occur following an allogeneic transplant, usually affecting the skin, liver, and GI tract. "Besides, amphiregulin is described to restore integrity of damaged intestinal mucosa in murine models of acute graft-versus-host disease (aGVHD)." (PMID 33717129, 2021).
adenoma (1 paper, 2013). A neoplasm arising from the epithelium. "Regardless, two ligands of the mammalian EGFR pathway, amphiregulin (AREG) and epiregulin (EREG), are induced by the pro-inflammatory cytokines IL-1β and TNF-a in inflamed colonic mucosa and in adenomas and carcinomas of human colon, but not in normal colonic mucosa." (PMID 25437036, 2013).
airway hyperresponsiveness (1 paper, 2024). "ILC2s are able to rapidly produce large amounts of type 2 cytokines and growth factors, such as IL-5, IL-13, and AREG to initiate type 2 immune responses, induce eosinophilic lung inflammation, airway hyperresponsiveness, mucus hypersecretion, and to drive healing and fibrotic repair." (PMID 39405112, 2024).
allergic rhinitis (1 paper, 2020). Inflammation of the nasal mucous membranes caused by an IgE-mediated response to external allergens. "Our results showed that AREG protein level in asthmatic patients' plasma and saliva correlate with clinical allergic phenotypes such as allergic rhinitis and atopy." (PMID 33195308, 2020).
autosomal dominant polycystic kidney disease (1 paper, 2018). Autosomal dominant form of polycystic kidney disease. "In autosomal dominant polycystic kidney disease, the use of anti-AREG antibodies and inhibitors of activator protein-1 (AP1) can reduce cell proliferation in cystic cells by reducing AREG expression and EGFR activity." (PMID 30670929, 2018).
AV block (1 paper, 2021). "While Cx43 deletion from macrophages prolonged AV conduction, it did not cause advanced AV block, suggesting that additional mechanisms, such as AREG-mediated facilitation of intramyocardial electrical coupling, are critically involved in AV nodal conduction." (PMID 33771995, 2021).
biliary atresia (1 paper, 2025). A rare, biliary tract disease characterized by progressive obliterative cholangiopathy of the intra- and extrahepatic bile ducts, occurring in the embryonic/ perinatal period, leading to severe and persistent neonatal jaundice and acholic stool. "As liver MAIT cell levels are correlated with the survival of biliary atresia patients after surgery and histological fibrosis, targeting AREG in biliary atresia would be a potential therapeutic strategy." (PMID 40725192, 2025).
bone sarcoma (1 paper, 2015). A sarcoma that arises from the bone. "Our findings indicated that AREG plays a critical role in tumor invasion and tumorigenesis of bone sarcomas." (PMID 26503469, 2015).
breast adenocarcinoma (1 paper, 2023). "We also used the human breast adenocarcinoma MCF-7 cell line as the positive control, as MCF-7 cells are known to secrete AREG." (PMID 37686213, 2023).
cartilaginous tumors (1 paper, 2021). "In bone-cartilaginous mesenchymal tissue, the important physiological role of amphiregulin in bone formation process and its prognostic role in malignant cartilaginous neoplasms have been previously documented." (PMID 34468540, 2021). "The aim of this study was to evaluate the role of amphiregulin protein, an epidermal growth factor receptor ligand, in cartilaginous tumors." (PMID 34468540, 2021).
chronic pancreatitis (1 paper, 2022). A chronic inflammatory process causing damage and fibrosis of the pancreatic parenchyma. "We also evaluated the presence of both CD90 and amphiregulin in human chronic pancreatitis by studying in histology sections of pancreas tissue." (PMID 35922425, 2022).
clear-cell carcinoma (1 paper, 2021).
cognition impairment (1 paper, 2025). "In addition, the expression of ALB, AREG and FCGR2B was notably elevated in hippocampus of DM mice, showing that these proteins may be closely associated with cognition impairment of DM mice." (PMID 40537751, 2025).
colorectal tumors (1 paper, 2024). "OSBPL2 was negatively correlated with VCAN, AREG, and EREG, whereas there was a positive correlation between VCAN, AREG, and EREG in colorectal tumors." (PMID 38267463, 2024).
crescentic glomerulonephritis (1 paper, 2024). A histopathologic term for a pattern of diseases characterized by extensive crescent formation in the glomeruli; patients present clinically with rapid deterioration of renal function, and possible progression to end-stage renal failure within weeks or months. "These authors also found a strong upregulation of renal AREG expression in human crescentic glomerulonephritis and thereby suggesting that AREG/EGFR axis might represent a new therapeutic target for patients with acute glomerulonephritis." (PMID 39234105, 2024).
cyst (1 paper, 2012). A sac-like closed membranous structure that may be empty or contain fluid or amorphous material. "The similarities in cyst AREG levels between non-mucinous and benign mucinous cysts may be related to the physiologic expression of AREG as part of a reparative process in combination with a smaller cellular mass of mucin producing cells." (PMID 22333441, 2012).
delirium (1 paper, 2026). A disorder characterized by confusion; inattentiveness; disorientation; illusions; hallucinations; agitation; and in some instances autonomic nervous system overactivity. "Other notable proteins robustly associated with delirium in our proteomic analysis are BCAN, SELENOP, AREG and MSLN." (PMID 41286463, 2026). "Overall, 14 out of the 19 stability-selected proteins still had a significant effect on incident delirium in the training set; however, only the AREG and MSLN proteins were consistently selected in the dementia-free subcohort (selection frequency >0.5)." (PMID 41286463, 2026).
diabetic nephropathy (1 paper, 2020). "In diabetic nephropathy, EGF receptor-dependent upregulation of YAP increases the levels of downstream profibrotic factors such as CTGF and amphiregulin." (PMID 33142952, 2020).
Dyskinesia (1 paper, 2023). A movement disorder which consists of effects including diminished voluntary movements and the presence of involuntary movements. "On immunofluorescence, AREG‐positive neurons were remarkably activated in the 12 mg/kg levodopa‐induced dyskinesia group." (PMID 37101388, 2023).
emphysema (1 paper, 2016). "Emphysema animals exhibited cardiorespiratory changes that resemble human emphysema, such as increased areas of lung hyperinflation, pulmonary amphiregulin expression, and diaphragmatic injury." (PMID 27761886, 2016). "Our emphysema model induced increased areas of lung hyperinflation, mean linear intercept, amphiregulin mRNA expression in lung tissue, and MAFbx expression in the diaphragm, the latter suggesting diaphragmatic atrophy." (PMID 27761886, 2016). "Amphiregulin is known to be higher in emphysema patients who exhibit damaged epithelium." (PMID 27761886, 2016). "Amphiregulin seems to be an important biological marker that could be used to monitor hyperinflation during mechanical ventilation in emphysema." (PMID 27761886, 2016).
gastrointestinal infections (1 paper, 2024). "In support of this, babies with homozygous mutations in EGFR, the receptor for amphiregulin and related EGFR-family ligands, develop recurrent skin and gastrointestinal infections, demonstrating the importance of EGFR-family ligands in maintaining tissue barrier protection." (PMID 38195661, 2024).
glucose metabolic disorders (1 paper, 2025). "However, to our knowledge, very limited research has been done on the possible role of AREG in glucose metabolic disorders." (PMID 39981678, 2025).
Hyperglycemia (1 paper, 2023). An increased concentration of glucose in the blood. "Importantly, amphiregulin was previously shown to be upregulated during beta cell recovery phase after transient hyperglycemia induced by deletion of the UPR sensor IRE1α24, suggesting a role for amphiregulin in modulating beta cell mass in response to ER stress." (PMID 37903947, 2023).
Hyperkeratosis (1 paper, 2018). Hyperkeratosis is a histopathological term defining a thickened stratum corneum and may be present in many different skin conditions, with many possible overlaps. "Concordantly, in Rhbdf2P159L/P159L mice, genetic deletion of Areg restores the normal skin phenotype, suggesting that AREG mediates the hyperplasia, hyperkeratosis, alopecia, and rapid wound-healing phenotypes in Rhbdf2P159L/P159L and Rhbdf2cub/cub mice." (PMID 30022999, 2018).
hypertrophic cardiomyopathy (1 paper, 2022). A condition in which the myocardium is hypertrophied without an obvious cause. "Our current results showed that AREG knockdown alleviated Ang II induced cardiac fibrosis in hypertrophic cardiomyopathy, which supported the influence of AREG on promoting cardiac fibrosis reported as previous studies." (PMID 35996142, 2022). "These outcomes showed that the level of AREG increased in hypertrophic cardiomyopathy." (PMID 35996142, 2022). "It is still unclear whether AREG modulate oxidative stress in hypertrophic cardiomyopathy." (PMID 35996142, 2022). "However, whether AREG can regulate hypertrophic cardiomyopathy is not well known." (PMID 35996142, 2022).
infarction (1 paper, 2025). A localised pathological necrosis of tissue resulting from obstruction of the blood supply usually by a thrombus, an embolus, or vascular torsion. "However, the temporal dynamics of AREG expression and the infiltration of AREG+ Tregs during post-infarction recovery remain unclear." (PMID 40495143, 2025).
inflammatory breast carcinoma (1 paper, 2018). An advanced, invasive breast adenocarcinoma characterized by the presence of distinct changes in the overlying skin. "Notably, while EGFR is overexpressed in around 50% TNBC and inflammatory breast cancers, we found that this gene, as well as its ligand AREG, was downregulated in the luminal A obese group." (PMID 29330624, 2018).
interstitial lung disease (1 paper, 2021). A diverse group of lung diseases that affect the lung parenchyma. "In particular, serum AREG levels in IIM patients with interstitial lung disease (ILD) were higher than those of HCs (22.4 pg/mL, p = 0.027)." (PMID 34442026, 2021).
intestinal cancer (1 paper, 2018). "These interesting data suggested that DCA affected the mRNA expression of AREG only in intestinal cancer cells, but not in precancerous cells." (PMID 29956475, 2018).
intestinal tumour (1 paper, 2018). "Real‐time PCR analysis was performed to measure AREG mRNA levels in intestinal tumour cells treated with DCA." (PMID 29956475, 2018). "It indicated a requirement of AREG for the DCA‐induced effects on EGFR‐Akt signalling pathway activation in intestinal tumour cells." (PMID 29956475, 2018). "Furthermore, immunostaining analysis in Apcmin/+ mice also suggested that releasing of AREG could activate EGFR/Akt pathway to further promote intestinal tumour development after DCA treatment." (PMID 29956475, 2018). "We found that DCA could activate epidermal growth factor receptor (EGFR) and promote the release of EGFR ligand amphiregulin (AREG), but not HB‐EGF or TGF‐α in intestinal tumour cells." (PMID 29956475, 2018).
invasive breast carcinoma (1 paper, 2021). A carcinoma that infiltrates the breast parenchyma. "AREG is co-expressed with AR in invasive breast cancer, which is reported as one of the prognostic biomarkers and therapeutic targets in invasive breast cancer, particularly in ER-negative breast cancer (MCF-7)." (PMID 34490085, 2021).
invasive carcinoma (1 paper, 2018). A carcinoma that is not confined to the epithelium, and has spread to the surrounding stroma. "However, lesions of age-matched AREG−/− PyMT mice showed more areas that had progressed to DCIS and invasive carcinoma." (PMID 30367629, 2018).
invasive ductal carcinomas (1 paper, 2018). "In The Cancer Genome Atlas database, luminal-B invasive papillary carcinomas have lower AREG expression than luminal B invasive ductal carcinomas." (PMID 30367629, 2018).
ischemic heart disease (1 paper, 2018). "Indeed, AREG expression was also elevated in cardiac tissues samples of patients with ischemic heart disease." (PMID 29483579, 2018).
latent infections (1 paper, 2019). "In normal to latent infections, we identified eight genes, of which three genes (FZD2, NDUFS8, NLRC4) were up-regulated, and another five genes (CCL4, IL1B, IL1A, TNF, AREG) were down-regulated." (PMID 31749827, 2019).
leukemia (1 paper, 2025). A malignant (clonal) hematologic disorder, involving hematopoietic stem cells and characterized by the presence of primitive or atypical myeloid or lymphoid cells in the bone marrow and the blood. "For instance, Th9 cells, known to produce the tissue-repairing factor amphiregulin, have been shown to reduce allogeneic transplant toxicity by preserving graft-versus-leukemia effects while mitigating graft-versus-host disease." (PMID 40760097, 2025). "Additionally, amphiregulin-producing Th9 cells mediate tissue repair in allogeneic hematopoietic stem cell transplantation, balancing graft-versus-leukemia effects while mitigating graft-versus-host disease." (PMID 40760097, 2025).
liver inflammation (1 paper, 2020). "Conversely, the tissue protective role of Treg-derived amphiregulin was limited in CCl4-induced liver inflammation and fibrosis, despite the predominant expression of amphiregulin in hepatic Treg cells." (PMID 33178216, 2020).
lymphoid neoplasm (1 paper, 2021). A neoplasm composed of a lymphocytic cell population which is usually malignant (clonal) by molecular genetic and/or immunophenotypic analysis. "AREG expression was observed to be downregulated in myeloid and lymphoid neoplasms." (PMID 34390367, 2021).
meningioma (1 paper, 2019). A generally slow growing tumor attached to the dura mater. "Compared to the control group, Grade I meningioma patients showed increased serum levels of amphiregulin (AREG), CCL24, CD69, prolactin, EGF, HB-EGF, caspase-3, and decreased levels of VEGFD, TGF-α, E-Selectin, BAFF, IL-12, CCL9, and GH." (PMID 31649887, 2019). "Among those, our validation studies showed that the expression of amphiregulin is significantly upregulated in the meningioma tumor tissues, compared to the control NWM specimens." (PMID 31649887, 2019). "We found a significant increase in the gene expression levels of amphiregulin in the Grade I meningiomas, while the VEGF-D mRNA levels were relatively decreased, compared to the control NWM tissue samples." (PMID 31649887, 2019). "It is likely that elevated levels of amphiregulin in meningioma patient sera may reflect the response of immune system and/or the ongoing tissue repair owing to the tumor mass." (PMID 31649887, 2019). "Our study identified two different ligands of EGFR, amphiregulin (AREG) and heparin-binding EGF (HB-EGF) that are elevated in the sera of Grade I meningioma patients." (PMID 31649887, 2019). "Our validation studies in an independent set of meningioma tissue specimens provide further evidence that caspase-3, amphiregulin and VEFG-D might be promising markers to monitor the status of meningiomas through a non-invasive manner by using patient blood." (PMID 31649887, 2019). "Alternatively, amphiregulin and HB-EGF may act as activators of EGFR that is overexpressed in meningiomas, supporting tumor growth and malignancy." (PMID 31649887, 2019).
metastasis (1 paper, 2016). The spread or migration of cancer cells from one part of the body (where they first appeared) to another. "Factors at the 0.10 level in the univariate analysis (TNM stage, tumor differentiation, tumor size, Resection margins, lymph node metastasis, AREG expression and AREG/EGFR co-expression) were entered into a multivariate survival analysis." (PMID 27391842, 2016).
monoclonal gammopathies (1 paper, 2019). "By analyzing the mRNA expression level of EGFR ligands in a published dataset (accession number GSE16122), we found that CD138+ cells expressed AREG mRNA at variable levels among the different type of monoclonal gammopathies." (PMID 30621731, 2019).
myocardial ischemia (1 paper, 2018). A disorder of cardiac function caused by insufficient blood flow to the muscle tissue of the heart. "Together these findings indicate that AREG-dependent signaling events through the ErbB1 receptor promote cardioprotection from acute myocardial ischemia and reperfusion injury." (PMID 29483579, 2018). "Other studies have indicated that AREG signaling dampens acute inflammation, such as occurs in the context of myocardial ischemia and reperfusion injury." (PMID 29483579, 2018). "In the present study, AREG expression during myocardial ischemia, exogenous AREG administration or Hif2a expression, and HIF2-alpha stabilization all increased the activated form of AKT." (PMID 29483579, 2018). "Consistent with a functional role for myocardial ischemia in AREG induction, AREG protein levels were elevated in patients with IHD compared to healthy controls." (PMID 29483579, 2018).
oral carcinomas (1 paper, 2016). "Moreover, OSCC had higher AREG expression than SCC from oropharynx and larynx, suggesting that AREG expression was particularly deregulated in oral carcinomas." (PMID 27669890, 2016).
osteoarthritis (1 paper, 2022). A noninflammatory degenerative joint disease occurring chiefly in older persons, characterized by degeneration of the articular cartilage, hypertrophy of bone at the margins and changes in the synovial membrane. "Interestingly, a previous study has shown that AREG interacts with EGFR, activating PI3K/Akt, and subsequently inducing the NF-κB transcription factor interaction with the MMP-13 promoter, inducing cartilage destruction in osteoarthritis." (PMID 35841013, 2022).
ovarian hyperstimulation syndrome (1 paper, 2022). A complication of ovulation induction in infertility treatment. "A recent study has found that elevated expression of AREG in GCs contributes to the development of ovarian hyperstimulation syndrome (OHSS), a condition thought to involve oxidative stress." (PMID 36466095, 2022).
Parasitic infection (1 paper, 2023). "Production of AREG, EGF, FGF-2, and IGFBP-3 was significantly higher in the intestinal mucosa of colitic mice with parasitic infection than in the intestine of mice without induced disease but infected with H. polygyrus." (PMID 36836678, 2023).